NEAT1 (nuclear paraspeckle assembly transcript 1)
Diseases named in the same sentence as NEAT1 in open-access papers (continued):
Sharing a sentence is not in itself a finding about the gene and the disease.
atherosclerosis (29 papers, 2019 to 2026). A disease characterized by the build-up of fatty material and calcium deposition in the arterial wall resulting in partial or complete occlusion of the arterial lumen. "Besides, ADAR1‐induced A‐to‐I RNA editing could stabilize the atherosclerosis‐associated NEAT1 lncRNA expression." (PMID 35718942, 2022). "A new study finds that aerobic exercise can slow the development of atherosclerosis by modulating the long non-coding RNA (lncRNA) NEAT1 to reduce its expression." (PMID 39901899, 2025). "This study aimed to investigate the role and mechanism of long noncoding RNA nuclear-enriched abundant transcript 1 (NEAT1) in macrophage ferroptosis during atherosclerosis (AS)." (PMID 41268533, 2025). "Our findings identified the direct interaction between enhancer of zeste homolog 2 (EZH2) and NEAT1 during atherosclerosis." (PMID 38646788, 2024). "In the current research, we have made a novel discovery that the long noncoding RNA Neat1 plays a critical role in the phenotypic switching of vascular smooth muscle cells (VSMCs) during the development of atherosclerosis (AS)." (PMID 38646788, 2024). "Nuclear paraspeckle assembly transcript 1 (NEAT1) is a lncRNA involved in multiple pathological mechanisms in atherosclerosis, such as apoptosis, foam cell formation, and inflammation." (PMID 39742258, 2024). "Whereas knockdown of NEAT1 in macrophages represses inflammation and the formation of foam cells, suggesting a role for NEAT1 in atherosclerosis development." (PMID 38170281, 2024). "NEW & NOTEWORTHY Our study demonstrates that the upregulation of long noncoding RNA nuclear paraspeckle assembly transcript 1 (NEAT1) promotes proliferation and migration during phenotypic switching of vascular smooth muscle cells in atherosclerosis." (PMID 38646788, 2024). "In contrast to ANRIL and NEAT1, lincRNA-p21 reduce atherosclerosis progression by influencing miR-221/SIRT1/Pcsk9 axis." (PMID 37508497, 2023). "NEAT1 can also contribute to atherosclerosis progression through oxidative stress and inflammatory pathways." (PMID 37508497, 2023). "Interestingly, lncRNA MALAT1 and NEAT1 have been found to serve as novel immunoregulators affecting monocyte‐macrophage functions and their disruption may contribute to identifying high risk in post‐MI and atherosclerosis patients." (PMID 33080104, 2020). "This was investigated in another study on atherosclerosis, in which a reduction of inflammation was observed following the inhibition of nuclear enriched abundant transcript 1 (NEAT1) and subsequent overexpression of miR-342-3p." (PMID 33003647, 2020). "Recently, a few lncRNAs, such as GAS5, NEAT1 and MALAT1 were reported to be associated with regulating atherosclerosis progression and prognosis." (PMID 30873207, 2019). "Therefore, by reducing the expression of NEAT1, exercise helps to inhibit endothelial cell death, thereby ameliorating atherosclerosis." (PMID 39901899, 2025). "NEAT1 may play a significant role in atherosclerosis development, as blocking NEAT1 reduces lipid uptake in human macrophage THP-1 cells." (PMID 39273193, 2024). "In summary, we have identified NEAT1 as an upregulated lncRNA in atherosclerosis." (PMID 38646788, 2024). "It has been shown that the long subtype of NEAT1 is critical in all stages of atherosclerosis." (PMID 37663249, 2023). "Furthermore, CXCL8 involved in the regulatory process of NEAT1, a long non-coding RNAs, on atherosclerosis." (PMID 36062083, 2022). "It is likely that the direct interactions between MALAT1 and NEAT1 through the enzymatically MALAT1‐derived mascRNA might promote the development of atherosclerosis." (PMID 33080104, 2020). "For example, interactions among MALAT1, NEAT1, and key immune effector molecules could regulate the development of atherosclerosis." (PMID 30873207, 2019). "Interestingly, NEAT1 may also play a pivotal role for the development of atherosclerosis where blocking of NEAT1 represses lipid uptake in human macrophage THP-1 cells." (PMID 38212456, 2024).
atherosclerosis (continued). "Previous studies have highlighted the significant roles of NEAT1 and XIST in the progression of atherosclerosis and CHD." (PMID 41614904, 2026). "NEAT1 interacts with miR-128 and is involved in ox-LDL-induced inflammation and oxidative stress response in macrophages during atherosclerosis." (PMID 39742258, 2024). "Given that the stability of RNA edits induced pro-inflammatory transcripts (such as CTSS or NEAT1) is increased in ASCVD, increased RNA editing may aid the inflammatory process of atherosclerosis." (PMID 37663249, 2023). "Silencing of lncRNA NEAT1 by siRNA repressed lipid uptake and the inflammatory response by targeting miR-342-3p in THP-1 macrophage, providing a strategy to treat atherosclerosis." (PMID 37709486, 2023). "We previously found NEAT1−/− and MALAT1−/− mice to display massive atherosclerosis and vascular inflammation." (PMID 36552736, 2022). "A recent study found that exercise-induced significant down-regulation of m6A modification and METTL14, which bind to the m6A site of nuclear paraspeckle assembly transcript 1 (NEAT1) and decrease NEAT1 expression, thereby mitigating endothelial cell pyroptosis and atherosclerosis." (PMID 40662138, 2025). "NEAT1-/- and MALAT1-/- mice display massive atherosclerosis and vascular inflammation." (PMID 36615135, 2023). "The furoxan-induced depletion of hnRNPM concentrations in VSMCs may genuinely reduce NEAT1 stability and SMC proliferation, with a conceivable in vivo decrease in SMCs’ contribution to atherosclerosis." (PMID 37570694, 2023). "Mice devoid of NEAT1 or MALAT1 displayed immune disturbances affecting monocyte-macrophage and T cell differentiation, and an immune system highly vulnerable to stress stimuli and prone to the development of atherosclerosis." (PMID 37998395, 2023). "Their group observed that NEAT1 directly binds to miR-128 and through that interaction plays a role in oxidized low density lipoprotein (ox-LDL)-induced inflammation and oxidative stress in atherosclerosis development." (PMID 30717168, 2019). "Moreover, knockout of NEAT1 significantly decreased thelevels of IL-1β, IL-6, TNF-α and COX-2 in ox-LDL-stimulatedTHP-1 human macrophages, and the NEAT1/miR-342-3p/NFIA axis may be enrolled inthe inflammatory response and lipid uptake in atherosclerosis." (PMID 39077015, 2023). "Mice lacking the lncRNAs NEAT1 or MALAT1 displayed immune disturbances affecting monocyte-macrophage, as well as T cell differentiation, rendering the immune system highly vulnerable to stress stimuli, thereby promoting the development of atherosclerosis." (PMID 36615135, 2023). "Mice lacking lncRNAs NEAT1 or MALAT1 displayed immune disturbances affecting monocyte-macrophage and T cell differentiation and rendering the immune system highly vulnerable to stress stimuli, thereby promoting the development of atherosclerosis." (PMID 36552736, 2022).
Alzheimer disease (28 papers, 2012 to 2025). A progressive, neurodegenerative disease characterized by loss of function and death of nerve cells in several areas of the brain leading to loss of cognitive function such as memory and language. "For example, beta-secretase 1(BACE1)-AS, BC200, and NEAT1 have been associated with Alzheimer’s disease (AD)." (PMID 39920595, 2025). "For instance, high levels of BC1/BC200 and BACE1-AS have been implicated in Alzheimer's disease (AD) while NEAT1's in Huntington's disease (HD)." (PMID 24795650, 2014). "The identified potential interaction between lncRNAs BOK-AS1 and NEAT1 underscores the complex regulatory network of NEAT1’s associations with Alzheimer’s Disease, both in terms of memory impairment and its knockdown benefits, further consolidating its significance in neurological contexts." (PMID 38001964, 2023). "This includes Neat1 that plays a key role in the modulation of neuronal activity and hippocampal-dependent memory formation in mice and has been implicated in Alzheimer’s disease." (PMID 37122377, 2023). "Notably, aberrant NEAT1 expression is implicated in the pathogenesis of various neurodegenerative diseases, including Alzheimer’s disease (AD)." (PMID 33221742, 2020). "Interestingly, the overexpression of NEAT1 was linked to Alzheimer’s Disease (AD) and memory impairment in many studies, while its knockdown in mice leads to decreased memory deficit and increased dendritic spine density, and it has been suggested as plasma biomarker for AD progression." (PMID 38001964, 2023). "LncRNA NEAT1 had increased expression levels in the temporal cortex and hippocampus of Alzheimer’s disease patients." (PMID 41245147, 2025). "Subsequently, lncRNA NEAT1 was shown to act as a promoting factor for Alzheimer’s disease progression via modulation of the miRNA-124/BACE1 axis." (PMID 41245147, 2025). "It is suggested that the upregulated lncRNA NEAT1 in Alzheimer’s disease brain probably acts as part of a protective mechanism against neuronal death." (PMID 41245147, 2025). "Nuclear paraspeckle assembly transcript 1 (NEAT1), a long non-coding RNA, plays an important role in the progress of Alzheimer’s disease." (PMID 38331935, 2024). "In contrast, NEAT1 suppresses mitophagy in neuron and renal epithelial cells and exaggerates the pathogenesis of Alzheimer’s disease and diabetic nephropathy." (PMID 36430876, 2022). "Reportedly, lncRNA nuclear enriched abundant transcript 1 (NEAT1) aggravates Aβ-induced neuronal injury in Alzheimer’s Disease." (PMID 33522352, 2021). "In Alzheimer’s disease, NEAT1 promoted the autoacetylation of P300 and its acyltransferase activity, and altered the level of H3K27ac and H3K27cr simultaneously." (PMID 34262024, 2021). "In Alzheimer’s disease (AD), nuclear paraspeckle assembly transcript 1 (NEAT1), a long non-coding RNA, mediated the autoacetylation of p300, which altered the level of H3K27ac and H3K27cr and the transcription of endocytosis-related genes." (PMID 34262024, 2021). "Such regulatory networks have been reported involving NEAT1 in Alzheimer’s disease as well, but the knowledge is rudimentary." (PMID 34584188, 2021). "Recently, PRKXP1, SST and TNCRNA (also known as NEAT1, listed second by information gain) were identified by Squillario and Barla as part of a 39 gene signature implicated in Alzheimer’s disease." (PMID 23066814, 2012). "MEG3 and NEAT1 are related with Alzheimer’s disease and are involved in cognitive decline." (PMID 36710930, 2022). "Consequently, NEAT1 inhibits the degradation and regeneration of impaired mitochondria and promotes pathophysiological processes involved in Alzheimer’s disease." (PMID 35054896, 2022). "Recent studies have shown that NEAT1 was also involved in neuronal loss diseases and neurodegenerative disorders, such as amyotrophic lateral sclerosis (ALS), traumatic brain injury (TBI), Huntington’s disease (HD) and Alzheimer’s disease (AD)." (PMID 33221742, 2020).
Alzheimer disease (continued). "Alzheimer’s disease, often a late-stage development in VCI, sees NEAT1 playing a critical role in its onset and progression." (PMID 38543885, 2024). "The miR-26b-5p has been reported to be involved in mitochondrial dynamics and predicted to be a specific biomarker of Alzheimer’s disease, but the effect on NEAT1 or S100A2 has not yet been studied." (PMID 39739972, 2024). "CSC and CB microglia also express more GRID2, previously detected in brain microglia of Alzheimer’s disease donors, and more HIF1A and NEAT1, which may indicate a hypoxic stress response." (PMID 37217978, 2023). "Moreover, ROC curve was plotted to evaluate the biomarker potential of NEAT1 and BC200 lncRNAs for Alzheimer's disease." (PMID 35949493, 2022). "For these reasons, NEAT1 overexpression as a pathomechanism in Alzheimer’s disease is unlikely, although our data do not allow to fully reject this hypothesis." (PMID 29997370, 2018). "To verify whether NEAT1, HOTAIR, and MALAT1 expression is also altered in Alzheimer’s disease, we quantified their levels by qRT-PCR in the temporal cortex, hippocampus, and cerebellum of the same AD patients and age-matched healthy controls which were analyzed in our previous work." (PMID 29997370, 2018).
COVID-19 (28 papers, 2020 to 2025). A disease caused by infection with severe acute respiratory syndrome coronavirus 2. "Critically, overexpression of NEAT1 impairs cognitive function, whereas knockdown of NEAT1 improves memory in mice, in support of a functional role for NEAT1 upregulation in COVID-19-associated cognitive decline." (PMID 38410515, 2024). "For instance, metastasis-associated lung adenocarcinoma transcript 1 (MALAT1) and nuclear paraspeckle assembly transcript 1 (NEAT1) have been shown to be strongly associated with immune responses and possibly involved in the progression of the inflammatory process in COVID-19." (PMID 36852336, 2023). "The predicted lncRNA NEAT1 -hsa-miR-214-5p/hsa-miR-7-5p-IGF1R network may reduce the risk of death from ARDS in COVID-19 patients." (PMID 36204652, 2022). "We discovered the lung pathology-associated lncRNA DANCR and the nuclear paraspeckles forming neuroprotective lncRNA NEAT1 as potentially involved in the susceptibility to and consequences of COVID-19, in conjunction with acetylcholine and inflammation-regulating transcripts." (PMID 33163005, 2020). "Moreover, NEAT1 at the cutoff of 90.88 could also be used effectively in COVID-19 susceptibility with 96.3% sensitivity, 100% specificity, 100% PPV, 93% NPV, and 97.5% accuracy." (PMID 35982898, 2022). "The observed upregulation of GAS5, NORAD, BISPR, and NEAT1 in dRNA-seq of infected Calu-3 cells (1.03- and 1.11-fold) is consistent with upregulation of these lncRNAs in COVID-19 patients (1.05- and 1.17-fold) in the two datasets (GSE171110 and GSE157103)." (PMID 41267684, 2025). "NEAT1 expression is elevated in saliva and nasopharyngeal samples of COVID-19 patients and upregulated in lung epithelial cells." (PMID 41267684, 2025). "Multiple studies revealed that NEAT1 expression is highly expressed in PBMCs and the saliva of mild and severe patients infected with COVID-19." (PMID 40362651, 2025). "A recent study observed significant overexpression of NEAT1 in the blood of COVID-19 patients and found that NEAT1 is significantly correlated with cytokines such as IL-6, CCL2, and TNF-α." (PMID 40285022, 2025). "For example, lncRNA ROR1-AS1 and UGDH-AS1 have been reported to modulate immune response in the COVID-19 patients while NEAT1, MALAT1, and LINC00273 have been reported to modulate both immune and inflammatory response in severe COVID-19 patients." (PMID 38770134, 2024). "Our study is the first to detect decreased NEAT-1 and miR374b-5p expression in COVID-19 patients’ serums." (PMID 39729489, 2024). "In contrast to our results, many researchers reported that NEAT-1 was highly expressed in various samples from COVID-19 patients, such as saliva, serum, whole blood, lung cells." (PMID 39729489, 2024). "Our study is the first to detect decreased NEAT-1 and miR374b-5p expression in COVID-19 patients’ serum." (PMID 39729489, 2024). "Numerous studies based on bioassays have identified changes in NEAT1 and MALAT1 expression in COVID-19 that have been associated with viral replication." (PMID 36852336, 2023). "We also found the specific downregulation of NKG7 and NEAT1 in innate-like T cells and NKs in COVID-19 patients." (PMID 36992700, 2023). "The recent observation that NEAT1 is significantly higher expressed in patients suffering from severe as compared to mild COVID-19 also supports its important proinflammatory role." (PMID 35418991, 2022). "In terms of lncRNA expression, we found that NEAT1 was significantly overexpressed in both severe and moderate COVID-19 patients compared to controls, and this difference exceeded hundreds of folds." (PMID 35982898, 2022). "The specific mechanism of action of lncRNA DANCR/NEAT1-miR-19a-3p/miR-335-5p-HIF1a/CCR7/TLR4 in COVID-19 patients’ needs to be further elucidated." (PMID 36204652, 2022). "In the severe COVID-19 group, we observed that NEAT1 expression was negatively correlated with TLC and positively correlated with TUG1 and CCL2 expressions." (PMID 35982898, 2022).